IL4 (interleukin 4)
Diseases named in the same sentence as IL4 in open-access papers (continued):
Sharing a sentence is not in itself a finding about the gene and the disease.
tumor (continued). "By immunochemistry and ELISA, we found that the spleen and tumor tissues in DC-VEC group had increased number of activated CD4+ and CD8+ T cells and cytotoxicity cytokines of IFN-γ and IL-4, with decreased secretion of immune suppressive cells and cytokines." (PMID 28978039, 2017). "In order to investigate the cellular immune responses induced by LM4Δhly::E7 in tumor-bearing mice, the numbers of IFN-γ- and IL-4-secreting cells in splenocytes harvested 7 days after the second immunization were determined using an ELISPOT assay." (PMID 28706878, 2017). "In addition, mast cells may promote inflammation, inhibition of tumor cell growth, and tumor cell apoptosis by releasing interleukin (IL)-1, IL-4, IL-6, IL-8, monocyte chemotactic protein-3 and-4 (MCP-3 and MCP-4), transforming growth factor beta (TGF-β), and chymase." (PMID 29137286, 2017). "We administer either l1 or l2 or both to the tumor site, where l1 represents the implementation of CD4+ T cells and l2 indicates the implementation of IL-4." (PMID 29250133, 2017). "The identification of predictive genetic markers in PTGS2, IL4 and PIK3CA highlights, for the first time, the relevance of tumour microenvironment, inflammatory response and PI3K/AKT pathway activation in sunitinib treatment resistance." (PMID 28117391, 2017). "Injection of neutralizing anti-IL-4, -IL-10, or -TGF-β1 antibodies can prevent this tumor-induced functional transition, resulting in enhanced CD8+ CTL generation and protection against tumor growth." (PMID 28060744, 2017). "In contrast, some studies provide the finding that Th2-derived cytokines (IL-4, IL-5, IL-10, and IL13) show anti-tumor activities in vivo that are as strong as the anti-tumor activities of Th1 cytokines." (PMID 29299026, 2017). "There is suggestive evidence that maintenance of the testicular immune privilege and normal spermatogenesis are favored by a Th2-balanced cytokine milieu (IL4, IL5, IL13), in contrast to the Th1-driven immune environment of neoplasia." (PMID 29250030, 2017). "For example, cancer cells promote the production of IL-4 and down-regulate the expression of IFN-γ in the tumor microenvironment." (PMID 29299026, 2017). "Conversely, the anti-inflammatory cytokines IL4 and IL10 were found at significantly lower concentration in the spleen of only the orthotopic tumor-bearing group when compared to sham." (PMID 27901481, 2017). "The alternatively activated M2 macrophages are stimulated by IL4 and IL13, secrete IL10, transforming growth factor-β (TGF-β), and chemokines, and are involved in tissue remodelling and tumour progression." (PMID 29065107, 2017). "This study suggested that the IL-4 produced by CD4+ cells upon a chronic activation, promotes the polarization and pro-tumor bioactivity in macrophages, that in turn enhance tumor cells malignancy and metastasis." (PMID 28927416, 2017). "Thus, IL-4 may have distinct functions, depending on the tumor environment." (PMID 27148488, 2016). "rGal-9 enhanced cytotoxic T cell activity against tumor cells, enhanced IFN-γ and IL-4 production, and promoted dendritic cell maturation via Gal-9-Tim-3 interactions." (PMID 27253379, 2016). "Interleukin-4 (IL-4), known as a T helper type 2 (TH2), suppresses cancer-directed immune surveillance and increases tumor metastasis." (PMID 27895317, 2016). "Since AD is associated with allergen sensitization, elevated serum IgE and increased expression of Type 2 cytokines (IL-4, IL5, and IL-13) in both unaffected skin and skin lesions of AD, candidate gene studies for AD have also focused on the Th2 pathway." (PMID 27777593, 2016). "In summary, IR affects the miR-340/429/IL-4/β-catenin/Stat6 signaling axis through activation of JAK and JNK, effectively enhancing tumor progression and metastasis of human carcinomas." (PMID 27895317, 2016). "The results revealed that tumor volume and weight in B16F10 bearing IL-4 mice were much lower compared to non- transgenic mice." (PMID 26993600, 2016).
tumor (continued). "NPs encapsulated with tumor lysate were able to stimulate specific T cells to produce larger quantities of Th1 and Th2-based cytokines including IFN- γ and IL-4, respectively." (PMID 27782834, 2016). "Constitutive expression of IL-6, TGF-β1, IL-17A, VEGF, IL-4, IL-10 and IDO by tumor cells as a major component of immune escape and immunosuppression in human EOC." (PMID 27118139, 2016). "The invariant NKT cells from the alcohol-consuming, melanoma-bearing mice exhibit a high IL4/IFN-γ ratio, indicating that they express a cytokine profile favoring immune inhibition and tumor progression." (PMID 26695753, 2015). "A Th2-polarized T cell response, characterized traditionally by the cytokine IL-4 but also TNF-α and IL-6, has been shown to support tumor growth." (PMID 26207636, 2015). "We evaluated the ability of T cells to function and produce IFN-γ, IL-2, IL-4, and IL-17 upon short-term stimulation with PMA and found very few differences in functional T cell capacity between NCF1*/* and NCF1*/+ tumor bearing mice." (PMID 26076008, 2015). "The expression of vascular endothelial growth factor (VEGF) was measured in tumor sections and serum levels of INF-γ, and IL-4 were measured to evaluate the immune system function." (PMID 25919398, 2015). "Since control tumors were approximately 3 times larger than IL-4 expressing tumors at the time of resection (1300 vs 400 mm3), we wondered if some of the difference in metastasis frequency might be due to the differences in tumor sizes at the time of resection." (PMID 27563494, 2015). "In the same manner, MCs can participate in tumor rejection, producing and releasing TNF-α and molecules such as interleukin 1 (IL-1), IL-4, and IL-6 that kill tumor cells." (PMID 25648323, 2015). "We next explored the in vivo effects of cancer cell-derived IL-4 on tumorigenesis by orthotopically engrafting GFP-expressing EV-AC2M2 or IL4-AC2M2 cells into mouse mammary glands and comparing tumor growth and metastasis." (PMID 27563494, 2015). "In our system, M2a macrophages differentiated in the presence of IL-4 and MDA-MB231 CM had the potential for increased CD200R signaling which in vivo would indicate an immunosuppressive tumor-promoting environment." (PMID 26243145, 2015). "The co-administration of PAP-GMCSF, -IL2, -IL4 and -IL7 significantly prevented the tumor induction of PAP-RM9 cancer cells." (PMID 25632844, 2015). "Significant inhibition of the tumor growth was observed in the groups treated with both PAP-GMCSF alone and with the co-administration of PAP-GMCSF, -IL2, -IL4 and -IL7." (PMID 25632844, 2015). "CD4+ type II NKT cells produced more of IL-13 and IL-4 than type I cells, and the NKT cell-dependent IL-13 was necessary for tumor recurrence in a growth-regression-recurrence pattern 15-12RM fibrosarcoma tumor model." (PMID 25389427, 2014). "IL-4 and IL-13 were shown to be crucial mediators in the stimulation of invasion or immunosuppression by TAM in several tumor types." (PMID 24723924, 2014). "This review surveys the tumor-promoting and tumoricidal activities of several prominent cytokines: IFN-γ, TNF-α, TGF-β, IL-17, IL-23, IL-4, and IL-13, produced by three major subsets of T helper cells that interact with innate immune cells." (PMID 24672527, 2014). "In the present study we detected a Th2/Th3-type cytokine expression profile (IL-10, IL-4 and TGF-β1) in an HPV16-positive murine tumor model and found that this profile changes following treatment with the IL-12 gene." (PMID 24808638, 2014). "IL-4 increases surface MHC class II antigen expression in B cells and stimulates the growth of both helper and cytotoxic T cells, including tumor infiltrating lymphocytes." (PMID 26056588, 2014). "Those which have been found to suppress tumor growth include IL-2, IL-12, IL-13 and IFN (gamma, beta and alpha) while IL-4, IL-6, IL-8 and IL-10 predominantly contribute to tumor growth." (PMID 24997057, 2014).
tumor (continued). "The liver NKT cells activated with α-GalCer produce IFN-γ (as well as IL-4) to activate NK cells and CD8+ CD122+ T cells to acquire antitumor cytotoxicity, and tumor-specific CD8+ T cells are finally induced." (PMID 23372642, 2013). "In line with this, IL-4 has been described as a potent TH2 cytokine that was proposed to promote PDA tumor cell growth and thereby play an active role in tumor progression of this malignancy." (PMID 24098720, 2013). "Another three IL4 pathway genes (PRKCZ, PLCG1, PIK3CD) that were down-regulated with tumor progression showed further decreased expressions after chemotherapy in the current study." (PMID 23451142, 2013). "Tumor growth in the MMTV-neu model with activated neu transgene is also suppressed by treatment with cytokines, such as IL-4 and IL-12, which have both been reported to be modified by noni treatments." (PMID 22619689, 2012). "Using this model system, we demonstrate that the presence of M2 polarized macrophages that develop either after stimulation with IL-4 or upon extended co-culture with tumor cells and fibroblasts supports invasive growth of the SCC tumor cells in OTCs." (PMID 22792213, 2012). "Thus, in certain cases, effective GBM tumor eradication may occur in response to IL-4 and the concomitant recruitment of CD8+ T cells and eosinophils whereby the CD8+ T cells identify specific antigens and produce IFN-γ that enhances eosinophil activation and the release of cytotoxic granules." (PMID 22251275, 2012). "Activation of MDSCs not only requires tumour-derived factors (e.g., tumour-derived prostaglandin E2 (PGE2)) but also IFN-γ produced by T cells and factors secreted by tumour stromal cells (like IL-1β, IL-4, IL-6, IL-10, IL-13)." (PMID 22778767, 2012). "The uptake of apoptotic tumor cells induced a massive production of IL-6 in both IFN-DC and IL-4-DC, while the production of IL-23 was selectively induced in IFN-DC." (PMID 21387004, 2011). "In this study, CD4+ T cells produced GM-CSF at significantly higher levels than TNF-α, IL-4, and IFN-γ in response to tumor lysates." (PMID 21931646, 2011). "Tumor-educated BAL macrophages produced significantly more IGF-1 than naïve macrophages, both basally and in response to IL-4 stimulation." (PMID 21699731, 2011). "However, IL-4 can have a cell antiapoptotic property which could help tumour growth." (PMID 20049171, 2009). "Within the tumour samples, we examined the correlation between SABT1 and the downstream regulated genes: IL-4, IL-13 and MAF-1 using Pearson's correlation coefficient." (PMID 19642980, 2009). "Down-regulation of IL4 Stat, which is an important regulator of signalling from IL13 through the IL4R–STAT6 pathway, is necessary for down-regulation of tumour immuno-surveillance from NKT cells." (PMID 12402156, 2002). "Several in vitro studies stress a potentially important role of interleukin 4 (IL-4) and the related gp200-MR6 molecule in the immunological response to cancer and in tumour proliferation." (PMID 8932345, 1996). "Our data indicate that NK cells isolated directly from the tumour site secrete more IFN-gamma and IL-4 than NK cells from the blood of the same patients." (PMID 1911184, 1991). "ELISA was performed to measure secretion of IL4, IL10, and TGFβ by tumor cells." (PMID 42094010, 2026). "IL-4 and IL-10 suppress antitumor adaptive immunity and promote HNSCC tumor growth." (PMID 41431358, 2026). "CD4+ T helper cells have a dual role: Th1 cells support antitumor responses and can directly kill tumor cells through cytokine release (IFN-γ and TNF-α), while Th2 cells promote tumor progression by secreting anti-inflammatory mediators, such as IL-4 and IL-13, that suppress immune activity." (PMID 41230456, 2025).
tumor (continued). "IL4: ipsilateral level IV lymph node; LVI: lymphovascular invasion; PNI: perineural invasion; ENE: extranodal extension; pT: pathological tumor size; pN: pathological nodal status; adjuvant RT: adjuvant radiotherapy; adjuvant CTRT: adjuvant chemoradiotherapy; pN3b: pathological nodal stage 3b." (PMID 41190196, 2025). "Compared with the negative control and GM/IL4-DC groups, FL/GM-DCs demonstrated an ability to inhibit tumor growth in the B16F10 model." (PMID 40977690, 2025). "IL-10 is generally considered as an immunosuppressive cytokine in the TME, so the decreased level of IL-10 is unlikely to be the reason for the accelerated tumor outgrowth, while the role of IL-4 in antitumor immunity is ambiguous." (PMID 40759573, 2025). "Furthermore, HMDMs treated with IL-4 + IL-13 separate from those exposed to untreated A375 conditioned media along PC2, in part due to the growth factors present in media from this tumor cell population, such as TGF-alpha and MFG-E8." (PMID 40539073, 2025). "In advanced stages, however, the balance shifts toward immunosuppressive populations such as M2 macrophages, Th2/Th17 cells, Tregs, and Bregs, which suppress immune responses through the secretion of factors like IL-4, IL-10, IL-17, and TGF-β, thereby facilitating tumor immune escape." (PMID 41384115, 2025). "SE modulated IL-2, IL-4, IL-6, IL-17, IFN-γ, and TNF-α in tumor environment." (PMID 40807278, 2025). "Induction of IL-4 under OXP indicates a shift toward an immunosuppressive environment, which may contribute to immune evasion by tumor cells." (PMID 39796244, 2025). "While immunosuppressive factors such as CCL2, CXCL12, IL-4, and IL-10 sustain an immune-excluded TME, pro-inflammatory mediators like IFN-γ, TNF-α, and CXCL10 counteract these effects by promoting immune cell infiltration and tumor suppression." (PMID 40330466, 2025). "Additionally, cytokine/chemokine multiplex analysis showed that FL/GM-DCs enhance anti-tumor immune responses by releasing cytokines such as IL - 12 and IFN-γ while producing lower levels of IL - 6 relative to GM/IL4-DCs." (PMID 40977690, 2025). "Again, there was a significant reduction in tumor growth in mice treated with IL-4+ gBT.Is but not in mice treated with irradiation only or mCherry+ gBT.Is." (PMID 40367186, 2025). "Using enrichment analysis, we identified several pathways that might be related to the tumor suppressor function of RASD1, such as the interleukin (IL)-4′s regulation of apoptosis." (PMID 40362656, 2025). "Cytokine expression analysis revealed upregulation of IL-1α, IL-2, IL-4, and TNFα and downregulation of IL-6 and IL-8 in JX14P TAMs compared to JX14P-RT TAMs, suggesting that JX14P-RT TAMs have a higher capacity for tumor-promoting inflammation." (PMID 40386422, 2025). "Mechanistic studies have elucidated IL-4’s interaction with its receptor, IL4-Rα, triggering upregulation of key anti-apoptotic mediators such as cFLIP, PED, FLAME-1, and Bcl-x(L), thereby facilitating tumor survival and advancement." (PMID 40507238, 2025). "To further determine the role of IL-4 in adaptive immune evasion, we studied cancer cell killing in co-cultures of A549 cells with tumor antigen-specific CD8+ T-cells with or without exposure to IL-4 and/or IFNγ + TNFα." (PMID 40091029, 2025). "Notably, we provide evidence of substantial Th2 cell infiltration at the bone metastatic site in LUADBM, indicating that Th2 cytokine IL4 activates IL4R signaling in tumor cells, facilitating tumor progression and metastasis." (PMID 39941924, 2025). "CD8+ effector and tissue-resident T cells expressed numerous IL-related receptor genes; however, they lacked stimulation from IL-related cytokines such as IL-2, IL-4, IL-7, and IL-15 when comparing response states between tumor and healthy groups." (PMID 40698080, 2025).
tumor (continued). "During the initiation phase, OGP significantly attenuated adenomagenesis in both the small and large intestine, decreased IL-6 and IL-4 levels, increased splenic anti-tumor CD8+ T cells, and diminished populations of tumor-promoting myeloid-derived suppressor cells." (PMID 40307509, 2025). "At the molecular level, the expression of Il4, Il17a, and Il33, but not that of Tslp, Ccl20 or Ccl27a, was dramatically lower in the skin lesions of the IL-1R antibody-treated SSKO mice than in those of their IgG-treated SSKO littermates." (PMID 39939818, 2025). "For example, the inverted cytokine receptor (ICR) of IL-4/IL-7, composed of the IL-4R extracellular domain and the IL-7R intracellular domain, reduces IL-4’s inhibitory effect on CAR-T cells, promoting T cell proliferation and enhancing anti-tumor activity." (PMID 39958351, 2025). "Microglia (BV2) and IL‐4‐treated BMDMs promote astrocytoma clustering and inhibit tumor growth, not shown in other macrophage cells." (PMID 40747560, 2025). "Similarly, IL-4-driven STAT6 signaling upregulates JMJD3, a histone demethylase that removes repressive H3K27me3 marks from TAM-related genes, sustaining the tumor-promoting macrophage phenotype." (PMID 41301911, 2025). "The Gas6/AXL pathway regulates angiogenesis, immune-related molecular markers, and the secretion of certain cytokines (MHC-I, PD-L1, IL-4, CCL3-5, and G-CSF) in the tumor microenvironment, and it also regulates the functions of various immune cells (NK, DC, M2, and Treg)." (PMID 40524208, 2025). "Clinical data show that chronic inflammation at tumor sites is often accompanied by elevated IL-4 levels, and IL-4-producing CD8+ T cells are less effective at tumor clearance compared with their non-IL-4-producing counterparts." (PMID 40864740, 2025). "Our findings suggest that therapeutic strategies combining direct tumor targeting with modulation of ASC-secreted factors—such as GROα, GM-CSF, EMMPRIN, or IL-4—may enhance treatment efficacy." (PMID 39796244, 2025). "In vivo antitumor efficacy was evaluated in LLC tumor-bearing mice through measurement of tumor growth inhibition, serum cytokine levels (IFN-γ and IL-4) by ELISA, and expression levels of IFN-γ and granzyme B (GZMB) within tumor tissues via immunohistochemistry." (PMID 40872601, 2025). "In colorectal cancer, tumor cells release IL-4 to promote the expression of CD155 on TAMs,108 thus facilitating their M2 polarization and increasing the expression of IL-10 and TGF-β, thereby supporting tumor progression." (PMID 40055311, 2025). "Directly comparing these parameters with DCs generated by the conventional GM-CSF/IL-4-based method (GM/IL4-DCs), our findings demonstrate that FL/GM-DCs effectively reshape the tumor microenvironment, contributing to long-term immune remodeling and functional persistence." (PMID 40977690, 2025). "To investigate the role of M2 macrophages in tumor growth, we differentiated THP-1 cells with PMA for 48 h and subsequently induced M2 polarization through additional treatments with human recombinant IL-4 and IL-13 for 48 h." (PMID 40807274, 2025). "During the tumor formation in B16F10 cell-challenged C57BL/6 mice, serum levels of several cytokines were monitored using ELISA to evaluate the effect of Hcs treatment: IL4, IL10, and IFNγ." (PMID 38786612, 2024). "For IL-4, the mean negative control level was 3.59 pg/mL ± 2.97, while the mean positive tumor was 7.53 pg/mL ± 3.12." (PMID 39062070, 2024). "Furthermore, the hyperactivation of miR-155 by STAT5 contributes to a TH2 phenotype, which, through its cytokines (IL-4, IL-5, and IL-13), inhibits the TH1 response, preventing an adequate defense of the organism against the tumor." (PMID 38435536, 2024).